SLC7A2 (solute carrier family 7 member 2)
Description:
Functions as a permease involved in the transport of the cationic amino acids (L-arginine, L-lysine, L-ornithine and L-homoarginine); the affinity for its substrates differs between isoforms created by alternative splicing. May play a role in classical or alternative activation of macrophages via its role in arginine transport (By similarity). [Isoform 1]: Functions as a permease that mediates the transport of the cationic amino acids (L-arginine, L-lysine, L-ornithine and L-homoarginine). Shows a much higher affinity for L-arginine and L-homoarginine than isoform 2. [Isoform 2]: Functions as a low-affinity, high capacity permease involved in the transport of the cationic amino acids (L-arginine, L-lysine, L-ornithine and L-homoarginine).
Synonyms: CAT-2; CAT2; ATRC2; HCAT2; SLC7A2A; SLC7A2B; CAT-2A; CAT-2B
Tractability: Antibody: UniProt places it where antibodies can reach, with high confidence; its Gene Ontology location is reachable by antibodies, with high confidence; UniProt predicts a signal peptide or a membrane-spanning region; the Human Protein Atlas places it where antibodies can reach. PROTAC: ubiquitination databases record sites on it; its protein half-life has been measured.
Gene: Protein-coding gene on chromosome 8 (17,496,975 to 17,570,573, forward strand). Ensembl gene ENSG00000003989.
Subcellular location: Cell membrane
Subcellular location (Human Protein Atlas): Plasma membrane; Cell Junctions
Pathways (Reactome):
Transport of small molecules: Amino acid transport across the plasma membrane
Gene Ontology:
Molecular function: amino acid transmembrane transporter activity; basic amino acid transmembrane transporter activity; L-arginine transmembrane transporter activity; L-lysine transmembrane transporter activity; L-ornithine transmembrane transporter activity; transmembrane transporter activity
Biological process: L-lysine transmembrane transport; amino acid transport; L-arginine import across plasma membrane; L-ornithine transmembrane transport; transport across blood-brain barrier; amino acid import across plasma membrane; L-arginine transmembrane transport; regulation of macrophage activation; transmembrane transport
Cellular component: cell junction; plasma membrane; membrane
Genetic constraint (gnomAD): Loss-of-function variants: 46 observed, 52.07 expected, observed/expected ratio (o/e) 0.88, 90% interval 0.7 to 1.13. The upper end of that interval is the gene's LOEUF score, 1.13, which puts it in group 4 of 6, group 1 being the genes least tolerant of losing a copy. Missense variants: 950 observed, 790.69 expected, observed/expected ratio (o/e) 1.2, 90% interval 1.14 to 1.27. Synonymous variants: 345 observed, 307.66 expected, observed/expected ratio (o/e) 1.12, 90% interval 1.03 to 1.23.
Homologues: Orthologues: macaque SLC7A2 (97% identical), chimpanzee SLC7A2 (96% identical), rat Slc7a2 (92% identical), dog SLC7A2 (92% identical), pig SLC7A2 (92% identical), guinea pig SLC7A2 (91% identical), rabbit SLC7A2 (91% identical), mouse Slc7a2 (88% identical), tropical clawed frog slc7a2 (77% identical), zebrafish slc7a2 (65% identical), Drosophila melanogaster CG7255 (45% identical), Drosophila melanogaster CG5535 (41% identical), and 12 more. Paralogues in human: SLC7A1 (58% identical), SLC7A3 (54% identical), SLC7A14 (42% identical), SLC7A4 (39% identical), SLC7A6 (19% identical), SLC7A8 (19% identical), SLC7A7 (19% identical), SLC7A11 (18% identical), SLC7A5 (17% identical), SLC7A10 (17% identical), SLC7A9 (17% identical), SLC7A13 (15% identical).
Diseases named in the same sentence as SLC7A2 in open-access papers:
SLC7A2 is named in the same sentence as 48 diseases in open-access papers, as found by Europe PMC text mining. Sharing a sentence is not in itself a finding about the gene and the disease. The quoted sentences say what the papers report.
hepatocellular carcinoma (7 papers, 2021 to 2024). A malignant tumor that arises from hepatocytes. "Previous studies have demonstrated that lower SLC7A2 expression is associated with worse prognosis of ovarian cancer and hepatocellular carcinoma." (PMID 36639771, 2023). "Recent studies have shown that lower SLC7A2 expression is associated with worse prognosis of ovarian cancer and hepatocellular carcinoma, and SLC7A2 deficiency in inflammatory bowel tissues increases the risk of inflammation-associated colon tumorigenesis." (PMID 36639771, 2023). "Solute carrier family 7 member 2 (SLC7A2), a cationic amino acid transporter, is lowly expressed in ovarian and hepatocellular cancers, which is associated with their worse prognosis." (PMID 36639771, 2023). "In addition, it has been reported thatg9a-mediated H3K9me2 silences the expression of SLC7A2 in hepatocellular carcinoma (HCC), which results in the upregulation of CXCL1 expression and recruitment of MDSCs." (PMID 39080807, 2024). "Recent research demonstrated a correlation between reduced SLC7A2 expression and an unfavorable prognosis in patients with ovarian cancer and hepatocellular carcinoma (HCC)." (PMID 39382373, 2024). "Moreover, in hepatocellular carcinoma (HCC), G9a silences SLC7A2 expression to induce CXCL1, promoting the recruitment of bone marrow-derived suppressor cells (MDSC) to the microenvironment." (PMID 36713412, 2022). "In addition, SLC7A2 can down-regulate the expression of CXCL1 to inhibit the infiltration of myeloid-derived suppressor cells and the immune escape of hepatocellular cancer." (PMID 36639771, 2023). "Solute carrier family 7 member 2 (SLC7A2), which is also a constituent of the SLC carrier family, was found to be commonly lacking in most patients with hepatocellular carcinoma." (PMID 38609997, 2024).
ovarian carcinoma (7 papers, 2018 to 2024). A malignant neoplasm originating from the surface ovarian epithelium. "NUCB2 has been associated with poor prognosis in breast cancer, prostate cancer, endometrial carcinoma, and bladder cancer, while low expression levels of SLC7A2 in ovarian cancer were associated with a positive prognosis." (PMID 37894871, 2023). "Our study indicated that SLC7A2 was downregulated in ovarian cancer and identified SLC7A2 as a marker associated with protective prognosis in ovarian cancer." (PMID 32647070, 2020). "In addition, we highlighted the association between SLC7A2 and viability, invasion, migration of ovarian cancer cells." (PMID 32647070, 2020). "Cisplatin resistance was one of the causes of ovarian cancer recurrence, so we explored whether SLC7A2 is related to ovarian cancer's reactivity to cisplatin." (PMID 32647070, 2020). "Therefore, we identified SLC7A2 as a marker associated with survival in ovarian cancer and focused on SLC7A2 in further exploration." (PMID 32647070, 2020). "Ovarian cancer cells exhibit enhanced migration and invasion capabilities when SLC7A2 expression is downregulated due to genetic variation." (PMID 39382373, 2024). "At present, studies have found that SLC7A2 plays critical roles in ovarian cancer and breast cancer." (PMID 34108444, 2021). "For further validation of expression variation of SLC7A2, we compared its expression levels between ovarian cancer and normal ovarian tissues in the GSE27651 and GSE54388 datasets, respectively." (PMID 32647070, 2020). "To validate the prognostic value of SLC7A2 in ovarian cancer, we divided 58 patients in the GSE31245 datasets into two groups using the median mRNA expression level of SLC7A2 as a cutoff point." (PMID 32647070, 2020). "Relationships between SLC7A2 expression in epithelial ovarian cancer and clinicopathological parameters." (PMID 32647070, 2020). "Sixty patients with epithelial ovarian cancer were divided into high SLC7A2-expression groups and low SLC7A2-expression groups with the median -ΔCT as cutoff value." (PMID 32647070, 2020). "Through analysis in the cBioportal database, we identified deep deletion as one of the main mechanisms by which SLC7A2 is under-expressed in ovarian cancer." (PMID 32647070, 2020). "The Transwell experiments showed increased invasion and migration ability of ovarian cancer cells after SLC7A2 knockdown." (PMID 32647070, 2020). "In fact, SLC7A2 serves as a potential biomarker and therapeutic target for ovarian cancer." (PMID 34215221, 2021). "SLC7A2 was downregulated in ovarian cancer in both datasets." (PMID 32647070, 2020). "Furthermore, we examined the mRNA expression levels of SLC7A2 in our 60 primary ovarian cancer specimen and 20 normal ovarian tissues." (PMID 32647070, 2020). "Therefore, SLC7A2 might promote ovarian cancer progression by interacting directly or indirectly with these molecules." (PMID 32647070, 2020). "Therefore, deep deletion might be one of the main mechanisms by which SLC7A2 is under-expressed in ovarian cancer." (PMID 32647070, 2020). "To detect more potential mechanisms of SLC7A2 in ovarian cancer progression, we conducted GSEA analysis in ovarian cancer tissue from TCGA database and found that under-expressed SLC7A2 might promote ovarian cancer progression by promoting adhesion and proliferation of ovarian cancer cells." (PMID 32647070, 2020). "Thus, we speculated arginine deprivation might be a potential mechanism via which down-regulated SLC7A2 promoted ovarian cancer viability." (PMID 32647070, 2020). "We performed functional experiments after knockdown of SLC7A2 by siRNAs in the A2780 and OVCAR-3 cell lines to validate the function of SLC7A2 in ovarian cancer." (PMID 32647070, 2020). "More importance should be attached to SLC7A2 and other SLC family members in further studies of ovarian cancer and further explorations into relative molecular mechanisms are worth performing." (PMID 32647070, 2020).
ovarian carcinoma (continued). "However, the functions of SLC7A2 in ovarian cancer pathogenesis and progression have not been explored." (PMID 32647070, 2020).
breast carcinoma (4 papers, 2016 to 2023). "Studies had found that the expression levels of SLC7A2 were correlated with a survival advantage in patients with breast cancer." (PMID 32647070, 2020).
colitis (3 papers, 2016 to 2024). Inflammation of the colon. "Dysfunction in bile acid transporter ASBT (SLC10A2) is associated with colorectal cancer advancement, particularly in pediatric cases, and SLC7A2 deficiency exacerbates colitis and increases the risk of colitis-associated colon tumorigenesis." (PMID 38534987, 2024). "We assessed the role of SLC7A2 in murine infection with Citrobacter rodentium, an attaching and effacing enteric pathogen that causes colitis." (PMID 27783672, 2016). "In contrast, expression of macrophage SLC7A2 in the colonic tissue protected mice from dextran sulfate sodium (DSS)-induced colitis." (PMID 27783672, 2016). "Induction of SLC7A2 was upregulated in colitis tissues, and localized predominantly to colonic epithelial cells." (PMID 27783672, 2016). "Furthermore, we have shown that the Arg transporter SLC7A2 has a deleterious effect on C. rodentium colitis by favoring Arg uptake by enterocytes and Arg-dependent bacterial adherence, whereas we found here that Arg treatment protects animals from C. rodentium-induced colitis." (PMID 30972302, 2019). "In bone marrow chimeras, the recipient genotype drove the colitis phenotype, indicative of the importance of epithelial, rather than myeloid SLC7A2." (PMID 27783672, 2016).
colorectal cancer (3 papers, 2014 to 2023). A primary or metastatic malignant neoplasm that affects the colon or rectum. "Given that SLC7A2 is lowly expressed in other types of cancers, such as colorectal cancer and associated with the polarity of macrophage." (PMID 36639771, 2023). "SLC7A2 is essential for transport of L-arginine, lysine and ornithine and genetic polymorphisms in the SLC7A2 gene are associated with colorectal cancer progression." (PMID 32821544, 2020).
asthma (2 papers, 2007 to 2024). "Another gene, SLC7A2, encodes a cationic amino acid transporter and has been reported to be associated with inflammatory responses in asthma." (PMID 38183082, 2024). "Among the up-regulated genes were 3 associated with inhibition of proliferation (Gpnmb, Setd8, Runx2) and 1 promoting inflammatory and immune responses (Pik3cd), as well as 4 asthma-related genes (Arg1, Ccl24, Slc7a2, Mcpt1) identifiable only through qRT-PCR." (PMID 18087596, 2007). "The qRT-PCR analysis of these samples verified results for Ccl8 and indicated a down-regulation of 10 other asthma-related genes (Arg1, Ccl11, Ccl24, Ear11, Mcpt1, Sprr2a, Chi3l3, Chi3l4, Chia, Slc7a2) in EOO versus AOO mice." (PMID 18087596, 2007). "However, the few asthma/inflammatory genes that are differentially expressed (Pik3cd, Arg1, Slc7a2, Ccl24, Mcpt1) are all up-regulated in ETS-exposed mice." (PMID 18087596, 2007). "However, when examined by qRT-PCR, four asthma-related genes were identified as up-regulated (Arg1, Ccl24, Slc7a2, Mcpt1)." (PMID 18087596, 2007). "Four genes linked to asthma or lung inflammation (Arg1, Ccl24, Slc7a2, Mcpt1) that did not pass all the microarray filtering criteria were confirmed by qRT-PCR as being up-regulated in ESO versus ASO mice, which is consistent with an enhanced lung response in ETS-exposed mice." (PMID 18087596, 2007).
lung cancer (2 papers, 2023 to 2024). A malignant neoplasm involving the lung. "In non‐small cell lung cancer, SLC7A2 also functions as a tumor suppressor by regulating drug sensitivity, immune infiltration, and cell survival." (PMID 39382373, 2024). "To explore the potential function of SLC7A2 in the development of lung cancer, we established SLC7A2-silenced A549-shRNA-SLC7A2 and H460-shRNA-SLC7A2 cells using lentivirus-based siRNA technology." (PMID 36639771, 2023). "Therefore, higher SLC7A2 expression may be a protective factor for lung cancer, especially for NSCLC." (PMID 36639771, 2023).
melanoma (2 papers, 2018 to 2020). A malignant, usually aggressive tumor composed of atypical, neoplastic melanocytes. "Another arginine transporter, CAT-2 (SLC7A2), is highly expressed in BRAF (v-raf murine sarcoma viral oncogene homolog B1) inhibitor-resistant melanoma, displaying metabolic reprogramming from glucose to arginine dependence." (PMID 33511116, 2020).
breast tumours (1 paper, 2011). "SLC7A2 expression is higher in oestrogen receptor (ER)-positive breast tumours than in ER-negative ones." (PMID 21654678, 2011).
cognitive decline (1 paper, 2025). "Reduced SLC7A2 expression may worsen inflammation and neuronal damage, leading to cognitive decline in AD." (PMID 40430038, 2025).
eosinophilia (1 paper, 2025). "Another study indicates that SLC7A2-deficient mice had spontaneous inflammation in their lungs, and marked eosinophilia, associated with up-regulation of eotaxin-1, was present in the bronchoalveolar lavage fluid of 3-week-old SLC7A2-deficient mice." (PMID 40688069, 2025). "The eosinophilia was gradually replaced by neutrophilia in adult mice, while eotaxin-1 levels decreased and GRO-α levels increased, examination of DCs activation revealed increased DCs activation in the lungs of SLC7A2-deficient mice." (PMID 40688069, 2025).
gastric cancer (1 paper, 2021). A primary or metastatic malignant neoplasm involving the stomach. "A negative correlation was found between VSTM2L and CIMP, and a CIMP-related gene signature comprising six genes (VSTM2L, CST6, SLC7A2, RAB3B, IGFBP1, and EVX2) stratified gastric cancer patients into high‐ and low-risk groups with distinct prognoses." (PMID 35155565, 2021).
infectious colitis (1 paper, 2016). A viral or bacterial infectious process affecting the large intestine. "While SLC7A2 is known as a macrophage L-Arg transporter, our data indicate that upregulation of SLC7A2 during infectious colitis was mainly observed in the epithelium." (PMID 27783672, 2016).
keloid (1 paper, 2025). An irregularly shaped, elevated mark on the skin caused by deposits of excessive amounts of collagen during wound healing. "We then focused on comparing the expression differences of IGFBP2+ fib marker genes (IGFBP2, FGFBP2, OLFML2A, CPE, APOD, SLC7A2) between keloids and normal controls." (PMID 39902627, 2025). "IGFBP2+ fibs are distinguished by the expression of marker genes including IGFBP2, FGFBP2, OLFML2A, CPE, APOD, and SLC7A2, which are markedly upregulated in normal skin tissue relative to keloid tissue." (PMID 39902627, 2025).
lentivirus infection (1 paper, 2021). Virus diseases caused by the Lentivirus genus. "We analyzed the SLC7A2 expression in H22 cells and next used H22 cells to establish stable cell lines, H22-SLC7A2 with lentivirus infection." (PMID 34108444, 2021).
leprosy (1 paper, 2020). Leprosy is a chronic infectious disease affecting primarily the skin and peripheral nervous system. "The exonic variant rs13259978 in SLC7A2 was found to be associated with leprosy." (PMID 32373110, 2020). "Since SLC7A2 is an important component of the classic nitric oxide antimicrobial pathway in macrophages, this finding suggested the involvement of the nitric oxide microbicidal pathway in leprosy." (PMID 32373110, 2020).
liver cancer (1 paper, 2021). An epithelial or non-epithelial malignant neoplasm that arises from the liver. "Decreased SLC7A2 level induced the expression of multiple liver cancer-related genes, CXCL1 was strongly induced by deficient SLC7A2 expression." (PMID 34108444, 2021).
meningioma (1 paper, 2025). A generally slow growing tumor attached to the dura mater. "Single-cell analysis revealed that SLC7A1 and SLC7A2 are expressed in meningioma cells, exhibiting mutual exclusivity in expression, while SLC7A3 is barely expressed." (PMID 41184266, 2025).
migraine (1 paper, 2018). "The arginine transport facilitated by Slc7a2 can be associated with migraine because arginine is a chemical precursor to NO." (PMID 30618656, 2018).
non-small cell lung carcinoma (1 paper, 2020). A group of at least three distinct histological types of lung cancer, including non-small cell squamous cell carcinoma, adenocarcinoma, and large cell carcinoma. "SLC7A2 has also been found to play a role in radio-resistance of non-small cell lung cancer." (PMID 32821544, 2020).
Obesity (1 paper, 2025). Accumulation of substantial excess body fat. "Similarly, we have shown that the hepatic expression of SLC7A2 was downregulated in individuals with obesity and glucagon resistance to amino acid catabolism, although fasting arginine concentrations were similar compared to lean individuals." (PMID 40980546, 2025).
osteosarcoma (1 paper, 2017). A usually aggressive malignant bone-forming mesenchymal neoplasm, predominantly affecting adolescents and young adults. "Within osteosarcoma we identified that cells have higher expression of the SLC7A1 and SLC7A2 amino acid transporters, compared to the SLC7A3 and SLC7A4 transporters consistent with the established role of these isoforms in transporting arginine and other key amino acids such as lysine and ornithine." (PMID 28969007, 2017).
rhabdomyosarcoma (1 paper, 2017). A rare aggressive malignant mesenchymal neoplasm arising from skeletal muscle. "In rhabdomyosarcomas SLC7A1 and SLC7A4 were strongly expressed, with low SLC7A2 (SLC7A3 not available)." (PMID 28969007, 2017).
sarcopenia (1 paper, 2023). Progressive decline in muscle mass due to aging which results in decreased functional capacity of muscles. "Investigating the functional consequences of SLC7A2 dysregulation in aged muscle and its potential as a therapeutic target for preventing or reversing sarcopenia will be a warranted subject." (PMID 38203268, 2023). "In summary, all of these findings indicated that the upregulation of SLC7A2 during the aging process may have a significant role in influencing the proliferation and differentiation of myoblasts, thereby playing an important role in combating the development of sarcopenia." (PMID 38203268, 2023).